TLR7 (toll like receptor 7)
Diseases named in the same sentence as TLR7 in open-access papers (continued):
Sharing a sentence is not in itself a finding about the gene and the disease.
lupus (continued). "For investigators who are focused on murine models of lupus nephritis, this model is not ideal for use in B6 mice, however topical TLR7 agonists may be useful as inducers or accelerants of autoimmunity and other lupus-like manifestations." (PMID 31998321, 2019). "Moreover, mice lacking Gfi1 have recently been reported to develop a TLR7-dependent lupus-like phenotype, which the authors showed to involve excess NFκB signaling." (PMID 31659207, 2019). "Thus, normalizing CD19+ B cell TLR7 expression in transgenic Tg7Sle1B6 mice overexpressing TLR7 in a lupus-prone background normalized lymphocyte activation but not proliferation." (PMID 29650017, 2018). "Several lines of evidence have revealed inappropriate activations of TLR7, TLR8, and TLR9 in systemic lupus erythematosus (SLE) and several other autoimmune diseases." (PMID 28061847, 2017). "Negative regulation of type I IFN through TLR-7 pathway by miR-146a was identified to inhibit the expression of STAT-1 and interferon regulatory factor 5 (IRF-5) in systemic lupus erythematosus (SLE) patients." (PMID 31557989, 2016). "However there was no clear effect of either Yaa status or Tlr7 dose on selection against known lupus related autoreactive specificities in the follicular repertoire." (PMID 25794167, 2015). "Two recent studies have shown that in lupus models the complete absence of TLR7 compromises B cell survival and abrogates spontaneous germinal center formation and the production of anti-Sm/RNP, anti-dsDNA, anti-cardiolipin (CL) and anti-nucleosome antibodies in a B cell intrinsic manner." (PMID 25794167, 2015). "Both TLR8−/− and TLR8−/− TLR9−/− mice could develop lupus phenotype by lacking their inhibitory effects on TLR7 signal." (PMID 26068236, 2015). "Furthermore, stimulation of TLR7 with a synthetic agonist in lupus-prone mice lacking the alpha oestrogen receptor led to a lower IL-6 synthesis by lymphocytes B than in wild type animals." (PMID 24692849, 2014). "TLR7/8 and TLR9 signaling pathways have been extensively studied in systemic lupus erythematosus (SLE) as possible mediators of disease." (PMID 25485543, 2014). "Additionally, studies of animals lacking TLR7 and 9 genes in a lupus background have shown reduced disease onset and development." (PMID 23936008, 2013). "TLR7 and TLR9 recognition of self-RNA and self-DNA, respectively, contributes to autoimmune diseases such as systemic lupus erythematosus (SLE)." (PMID 23426999, 2013). "However, in systemic lupus erythematosus (SLE), endogenous nucleic acids within immune complexes containing nuclear particles reach endosomes via FcR-mediated phagocytosis before they can interact with TLR7 and TLR9." (PMID 23803655, 2013). "Therefore, the aberrant activation of TLR7 might induce LMP1 expression and LMP1-expression cells may be producing IFNs in lupus patients." (PMID 22952664, 2012). "pDCs isolated from cutaneous lupus erythematosus and SLE patients administered HCQ had significantly lower IFNα production upon TLR7 or TLR9 stimulation compared with patients not receiving HCQ." (PMID 40746538, 2025). "Givne that, to our knowledge, there were no previous reports on whether TLR7 engagement ( a lupus-relevant pathway) would induce ACOD1, we performed an in vitro time-course on WT and Acod1−/− bone marrow-derived macrophages (BMDM) following incubation with IMQ." (PMID 38605883, 2024). "Thus, we hypothesized that the global absence of TLR9 may impact the way B cell–expressed TLR7 affects lupus." (PMID 37606042, 2023). "BXSB male mice, which develop lupus due to the Yaa locus on the Y chromosome, had ameliorated disease with early depletion of the pDC population, but whether this was dependent on pDC-intrinsic TLR7 was not tested." (PMID 37606042, 2023).
lupus (continued). "Exosomes derived from lymphocytic leukemia (CLL) can target TLR7 signaling to promote innate immunity, while exosomes isolated from systemic lupus erythematosus (SLE) patients' serum can produce abundant IFN-α, TNF-α, IL-1β, and IL-6 via the TLR1/2, TLR7, TLR9, and TLR4 pathways." (PMID 32565722, 2020). "A recent example of this is the implication of L. reuteri (strain SP-C2-NAJ0070) as an exacerbator of systemic lupus erythematosus (SLE) symptoms in a TLR7-dependent manner, an effect that is not attributable to other Lactobacilli." (PMID 32271839, 2020). "Since our earlier data showed that ligation of CD180 can negatively regulate TLR7- and TLR9-mediated activation of macrophages and DCs in vitro, we guess that ligation of CD180 may inhibit the activation of macrophages and DCs in vivo, and relieve the symptoms of lupus-prone mice." (PMID 30498494, 2018). "TLR7 and TLR8 have already been shown to play a central role for the recognition of self RNA in the immunopathogenesis of autoimmune diseases such as systemic lupus erythematosus (SLE), psoriasis, rheumatoid arthritis, Sjögren's syndrome and others." (PMID 24904837, 2014). "Treatments targeting TLR7/8 and TLR9 are in Phase I trials in patients with SLE and should provide insight into the role of TLR signaling in lupus including whether these therapies will be more effective in women than men." (PMID 25485543, 2014). "In addition, MRL/lpr lupus prone mice lacking endosomal TLR7 display ameliorated signs of disease." (PMID 23936008, 2013). "However, TLR7 and TLR9 were recently shown to have distinct effects in a murine model of Lupus and also during experimental West Nile Encephalitis, where Tlr7-/- mice, but not Tlr9-/- mice, showed an impaired CD45+ leukocyte and macrophage infiltration at the site of infection." (PMID 21253574, 2011). "For example, the Y264H mutation in TLR7 causes early-onset lupus, while TLR8 gain-of-function mutations result in recurrent infections, neutropenia, antibody deficiency, and BM failure, conditions not typical of SLE." (PMID 40910948, 2026). "The administration of anti-TLR7 monoclonal antibodies or the TLR7/TLR9 inhibitor IRS954 diminishes autoantibody production and glomerulonephritis in lupus-prone mice, suggesting that RNA-stimulated TLR7 signalling promotes leukocyte recruitment and autoantibody production in SLE." (PMID 39062948, 2024). "There are multiple immune active genes on the X chromosome, including TLR7, which has been shown to have dual expression in XX females and in XXY males (Klinefelter syndrome) in the immune system, with consequences for diseases including systemic lupus erythematosus (SLE)." (PMID 39286972, 2024). "Indeed, TLR8-deficient mice on the C57BL/6 background, which is not prone to lupus, develop SLE due to increased TLR7 expression and signaling by cDCs and pDCs." (PMID 36389822, 2022). "For instance, PBMCs obtained from patients with systemic lupus erythematosus that were treated with 50 nM of VitD3 express lower levels of TLR3, TLR7, and TLR9 compared to non-treated PBMCs, as observed in this study." (PMID 34634046, 2021). "Here, we show that the anti-mouse TLR7 mAb, but not anti-TLR9 mAb, protected lupus-prone NZBWF1 mice from nephritis." (PMID 34868046, 2021). "For example, TLR7 and TLR9 sense not only pathogen-derived nucleic acids, but also self-derived nucleic acids in noninfectious inflammatory diseases such as systemic lupus erythematosus (SLE) or hepatitis." (PMID 29988708, 2018). "In experimental lupus induced by 2,6,10,14-tetramethylpentadecane (TMPD, pristane), autoantibody production and nephritis are abolished in mice lacking either TLR7 or the IFN-I receptor." (PMID 26717913, 2015).
lupus (continued). "Plasmacytoid dendritic cells (pDCs) constitutively express two members of the Toll-like receptor (TLR) family, TLR-9 and TLR-7, through which they can be stimulated to produce high levels of interferon (IFN)-α, a key mediator of the pathogenesis of systemic lupus erythematosus (SLE)." (PMID 22734582, 2012). "ABCs are reduced in the absence of Bank1 in TLR7.tg6 and IMQ-treated lupus-prone mice." (PMID 39163122, 2024). "A previous study showed that TLR7/IFN-α-mTOR signaling was significantly activated in total MDSCs in mice with early-aged lupus, suggesting that the abnormal differentiation of MDSCs might provide an important insight into the early diagnosis and treatment of SLE." (PMID 34282122, 2021). "The involvement of IRAK-4 in TLR7 and TLR9 signaling, coupled with the observation that dual inhibition of TLR7 and TLR9 in lupus-prone mice results in amelioration of disease symptoms, indicates that IRAK-4 may be a suitable therapeutic target for systemic lupus erythematosus (SLE)." (PMID 19689377, 2009). "Because TLR7 but not the DNA sensor TLR9 is essential for development of lupus-like disease in multiple mouse models, autoimmune response to RNA-related self-antigens such as Sm/RNP appears to be crucial in development of SLE." (PMID 30333834, 2018).
viral infection (282 papers, 2008 to 2026). "One key immunological factor linked to sex differences in viral infections is the differential expression of toll-like receptor 7 (TLR7) between males and females." (PMID 40143355, 2025). "On the other hand, TLR7 activation has also been implicated in the development of AHR in the context of viral infections, as demonstrated in mice 42 days post-infection." (PMID 39614276, 2024). "Combinations of different alleles for variations in the TLR7 gene were associated with the evolution of viral infections." (PMID 39650644, 2024). "TLR7 is an important immune sensor and key driver of inflammation following viral infection that has been implicated in hyperinflammatory responses in autoimmunity, influenza and SARS-CoV2 infection." (PMID 37795093, 2023). "In TLR7-deficient mice, viral infection still induced the mRNA expression level of MyD88 and NF-κB but they were lower than those in wild type mice." (PMID 37089926, 2023). "Forsythiaside A was indicated to interfere with the activation of the TLR7 signaling pathway to influence the inflammatory response and the subsequent lung injury caused by viral infection." (PMID 37089926, 2023). "In this study, we examined the potential of the dual TLR7/8 agonist R848 to mimic the host response to an ssRNA virus infection and the associated behavioural response." (PMID 34991643, 2022). "As such, the TLR7 overexpression in women is associated with enhanced resistance to viral infections." (PMID 34203647, 2021). "TLR7 recognizes pathogenic single-stranded RNAs (ssRNAs) and plays a crucial role in the innate immune response to viral infections, such as human immunodeficiency virus 1 and influenza virus." (PMID 33060576, 2020). "Association of the TLR7 rs179010 minor allele T has been reported with several other viral diseases, for example chronic HBV infection in Chinese males, chikungunya virus infection in Indian males and dengue virus infection in Indian patients." (PMID 33193416, 2020). "Several lines of evidence related less susceptibility and severity and better outcomes of viral infections in women than men to increased TLR7 activity and/or expression." (PMID 32774170, 2020). "Frequent viral infections are associated with progression to asthma, which we have previously modelled in TLR7-/- mice and pDC-depleted mice." (PMID 32658914, 2020). "Previous studies showed that women are associated with increased stimulation of toll-like receptor-7 and interferon production after viral infection compared to men." (PMID 33374452, 2020). "The imidazoquinoline compound imiquimod, which is a TLR7 agonist appears to have anti-viral properties and has been used to treat viral infection associated with genital warts." (PMID 30787331, 2019). "Summarized, our data strongly point towards TLR3 and TLR7 as initiator of inflammation in RE, possibly underlying a viral infection or a post-infectious autoimmune encephalitis." (PMID 30663001, 2019). "During viral infection and associated TLR7/8 stimulation, macrophages produce various proinflammatory cytokines such as TNF-α and IL-6, which leads to an enhanced inflammatory response." (PMID 24191131, 2013). "As an existing example of virus infection, imiquimod, which is a TLR7 agonist, have been applied to an infectious disease caused by human papilloma virus, namely, condylomata acuminata." (PMID 20672047, 2010). "TLR7/8 are important for sensing single stranded RNA derived from RNA viruses, which are common causes of childhood viral infections including measles, rhinovirus (the most common cause of 'cold'), and influenza." (PMID 19025588, 2008). "Although TLR7 signaling in platelet activation historically has been studied in viral diseases such as EMCV-1, TLR7 has also been implicated in dysregulated and persistent inflammation in sepsis, secondary to the recognition of endogenous DAMPs, most notably ex-miRNAs." (PMID 41301522, 2025).
viral infection (continued). "Our study presents important information that may contribute to the context of personalized medicine, related to the prediction of prognosis of HTLV-1 infection, since mutations in TLR7 can influence the evolution of viral infections." (PMID 39650644, 2024). "Therefore, the present study reviewed the role of TLR7, 8, and 3 in inflammatory bowel disease as well as their association with viral infections and evaluated different antagonists for the treatment of IBD." (PMID 34659656, 2021). "Inflammatory conditions associated with an increase in IFNs production, such as viral infections, could promote TLR7 expression and drive Ab and cytokine production by TR B cells." (PMID 31231380, 2019). "We supposed that inhibition of TLR7 may contribute to a M1-/M2-like mixed macrophages polarized activation caused by virulent strain NDV at the later stages of viral infection." (PMID 29670609, 2018). "Thus, we identify HRS as a key regulator of TLR7 signaling and illustrate a novel mechanism underlying the regulation of host immunity and inflammation during viral infection." (PMID 28854257, 2017). "Moreover, mononuclear cells in females produce higher amount of INF-a by TLR7 stimulation thus can cause stronger innate immunity against viral infections." (PMID 29308383, 2017). "The Toll-like receptor 7 (TLR7) gene, encoded on the X chromosome, is another gene that may escape X inactivation, resulting in a higher expression level of TLR7 in female immune cells, which causes more cytokine production against viral infection." (PMID 35664675, 2022). "This work demonstrates a novel and important role for sEV packaged TLR7/8 activating-miR-146a-3p in FM inflammatory responses to viral infections." (PMID 42189811, 2026). "TLR7, a Toll-like receptor, is involved in recognizing single-stranded RNA, which can be found in viral infections and also in some cancer cells." (PMID 40853959, 2025). "Engagement of TLR7/8 receptors in macrophages contained in PBMC cultures mimics their detection of single-stranded RNA (ssRNA) viral infections (e.g., coronaviruses, influenza viruses and RSV)." (PMID 40432075, 2025). "Background/Objectives: Activation of the Toll-like receptor 7 (TLR-7) plays an important role in the pathogenesis of many autoimmune diseases and viral infections." (PMID 40574053, 2025). "In both studies, significant upregulation of the LrTLR7 gene expression was observed, suggesting the possible role of TLR7 in recognizing dsRNA-viral infection." (PMID 40352938, 2025). "Berberine suppressed the upregulation of the TLR7 signaling pathway (such as TLR7, MyD88, and NF-κB (p65)) induced by viral infection at both the mRNA and protein levels." (PMID 40050867, 2025). "Next, we investigated the relevance of the SLC15A4-TASL pathway in the context of LCMV cl.13 viral infection, whose long term control critically depends on TLR7 and was reported to be compromised in feeble mice." (PMID 39856058, 2025). "This was orchestrated by ICAM-I and αLβ2-integrin and TLR7, in agreement with results obtained for other viral infections." (PMID 40175091, 2025). "In particular,TLR7 has been identified as a key player in the innate immune responseagainst viral infections and small-molecule TLR7 agonists have shownpotential for vaccine therapy, for treatment of asthma and allergies,and as anticancer drugs." (PMID 38250345, 2024). "TLR7, which recognizes viral RNA, is present in pDC endosomes, and recognition of viral RNA by this receptor during a viral infection induces an antiviral infection cascade through the production of IFNα and other factors." (PMID 38957464, 2024). "TLR7 is mainly expressed in pDCs and plays an important role in providing protection against viral infections." (PMID 39464882, 2024). "TLR4 is a key signalling pathway in acute lung inflammation, and TLR7/8 also plays a key role in inflammatory signalling in response to viral infections in the lung including severe influenza and COVID-19." (PMID 39137914, 2024).